ETS1 (ETS proto-oncogene 1, transcription factor)
Diseases named in the same sentence as ETS1 in open-access papers (continued):
Sharing a sentence is not in itself a finding about the gene and the disease.
glioma (continued). "Here, we report a similar signature whereby TWEAK-induced p52 activity resulted in the increased enrichment of oncogenic motifs, such as various ETS factors, KAISO and ZEB1, at ETS1 binding sites and augmented genome-wide ETS1 DNA binding, which altered the transcriptomic landscape of gliomas." (PMID 37087499, 2023). "Intriguingly, the ETS1 and p52-dependent DEGs were specifically enriched for terms associated with cell migration, VEGF production and MAPK activation, which drive glioma development and progression." (PMID 37087499, 2023). "We searched for transcription factors that are positively co-expressed with EIF4EBP1 in gliomas and found EIF4EBP1 mRNA expression to be significantly and positively associated with the mRNA expression levels of MYBL2, FOXM1, ETS1, HIF-1A, JUN, E2F1, and E2F6 in the REMBRANDT dataset." (PMID 35228525, 2022). "The lncRNA PAXIP1-AS1/ETS1/KIF14 axis could be considered as a target for glioma therapy, because of its contribution to invasion, migration, and angiogenesis in glioma tumors." (PMID 34646821, 2021). "Additionally, a recent study found that in the BRAFV600E mutated glioma cells also carrying pTERT mutation, several members of ETS family were hyperactivated: ETS1, GABPA, GABPB, ETV1, ETV4 and ETV5." (PMID 33547950, 2021). "ETS1 upregulation in tumor ECs was dependent on TGFβ signaling, and targeting TGFβ signaling by inhibitor decreased tumor angiogenesis and vascular abnormality in CT-2A glioma model." (PMID 34867089, 2021). "Further, we probed the function of ETS1 in glioma and whether its regulatory role was mediated by SNHG10/miR-532-3p/FBXL19 pathway." (PMID 33298070, 2020). "ETS1 promotes angiogenesis by upregulating the expression of KIF14 in glioma." (PMID 33203790, 2020). "In addition, ETS1 has been suggested to elicit tumor-facilitating functions in glioma by several former researches." (PMID 33298070, 2020). "Thus, overexpressed lncRNA PAXIP1-AS1 enhanced glioma cell migration, invasion, and angiogenesis by recruiting transcription factor ETS1 to upregulate KIF14 expression." (PMID 31823805, 2019). "The transcription factor ETS1, acts as an oncogene and has a key role to play in glioma development, suggesting that its inhibition may comprise a potential therapeutic strategy for glioma." (PMID 31823805, 2019). "Overexpression of lncRNA PAXIP1-AS1 enhanced migration, invasion, and angiogenesis of human umbilical vein endothelial cells in glioma by recruiting the transcription factor ETS1 to upregulate the expression of KIF14, which was further confirmed by accelerated tumor growth in nude mice." (PMID 31823805, 2019). "Specifically, this study provides evidence suggesting that lncRNA PAXIP1-AS1 upregulates the expression of KIF14 by recruiting the transcription factor ETS1, which accelerates the development of glioma as reflected by enhanced glioma cell migration, invasion, and angiogenesis." (PMID 31823805, 2019). "ETS1 links these two driver alterations functionally and may represent a promising therapeutic target in this aggressive glioma subgroup." (PMID 31391125, 2019). "Therefore, we explored the regulatory mechanisms underlying the putative involvement of the lncRNA PAX-interacting protein 1- antisense RNA1/ETS proto-oncogene 1/kinesin family member 14 (PAXIP1-AS1/ETS1/KIF14) axis in glioma cell invasion and angiogenesis." (PMID 31823805, 2019). "Given that ETS-1 can induce the invasion and migration of rat C6 glioma cells, we next analyzed whether it was a miR-144-3p target." (PMID 26826553, 2016). "As this analysis has shown that all of these processes are co-ordinately regulated, the identification of two transcription factors that are associated with all or almost all of these modules suggests that both E2F4 and ETS1 play a significant role in the pathogenesis of glioma." (PMID 24523864, 2014). "In this regard, it is worth to mention that ETS-1 is closely involved in gliomas development." (PMID 19750005, 2009).
glioma (continued). "Moreover, Kita also confirmed that ITGA5, which was upregulated by Ets-1, could be secreted by glioma cells to boost tumor migration and invasion, finally contributing to glioma malignancy." (PMID 35371978, 2022). "The inhibition of ETS1 (avian erythroblastosis virus E26 oncogene homolog-1), a protooncogene transcription factor with a role in glioma development, may be a possible strategy for glioma treatment." (PMID 34646821, 2021). "Moreover, ETS1 upregulated the expression of KIF14 in glioma." (PMID 33203790, 2020). "Thus, a hypothesis that the lncRNA PAXIP1-AS1/ETS1/KIF14 axis has functional relevance in glioma pathology was framed and investigated." (PMID 31823805, 2019). "Conclusively, ETS1 acted as a transcription activator of SNHG10 and exhibited oncogenic properties via SNHG10/miR-532-3p/FBXL19 axis in glioma." (PMID 33298070, 2020). "More importantly, ETS1 promoted the transcription of SNHG10 and it mediated contribution to the malignant behaviors of glioma cells by SNHG10/miR-532-3p/FBXL19 signaling." (PMID 33298070, 2020). "The treatment of oe-PAXIP1-AS1 + sh-ETS1 or sh-KIF14 attenuated the migration and invasion ability of glioma cells (p < 0.05)." (PMID 31823805, 2019). "Accordingly, in contrast to TERT promoter wild-type glioma, ETS-factor inhibition by YK-4-279 reduced TERT mRNA expression in double-mutant cell models whereas ETS1 expression was more variable." (PMID 31391125, 2019). "Our data point towards cooperation of GABPA with ETS1, especially in a BRAFV600E-mutant glioma background." (PMID 31391125, 2019). "The key findings of this study highlighted the potential of the lncRNA PAXIP1-AS1/ETS1/KIF14 axis as a therapeutic target for glioma treatment, due to its role in controlling the migration and invasion of glioma cells and its angiogenesis." (PMID 31823805, 2019). "Our study highlights a previously unrecognised role of non-canonical NF-κB activation in ETS1 regulation, whereby p52-induced ETS1 expression results in a multitude of genomic, transcriptional and functional events in glioma cancers." (PMID 37087499, 2023). "LncRNA PAXIP1-AS1 is located in the glioma cell nucleus, where it could increase the promoter activity of KIF14 through recruitment of the transcription factor ETS1." (PMID 34646821, 2021). "As a result, ETS1/SNHG10/miR-532-3p/FBXL19 axis was discovered, which might provide a helpful theoretic basis for the exploration of new targets for glioma therapy." (PMID 33298070, 2020). "Cell behaviors in glioma could be orchestrated by lncRNA PAXIP1-AS1, due to its mechanistic function in mediating KIF14 via ETS1." (PMID 31823805, 2019). "ETS-1 protein is not only differentially expressed in astrocytes and astrocytoma cells but also regulates various targets such as Egr-1, cathepsin B and the urokinase-type plasminogen activator besides PP2A-Aα in gliomas." (PMID 19750005, 2009). "The roles of non-canonical NF-κB signalling and ETS1 have both been well documented to regulate glioma migration, invasion and cell proliferation Furthermore, p52 and ETS1 have been described to function cooperatively at the mutant TERT promoter to drive telomerase expression in gliomas." (PMID 37087499, 2023). "Hence, our results emphasise the relevance of non-canonical NF-κB activation and ETS1 in glioma progression, thereby highlighting the immense potential of targeting the p52-ETS1 regulatory axis in cancer therapy." (PMID 37087499, 2023). "In addition, ETS-1 expression correlates with microvessel density in some non-glial tumors and is an independent negative prognostic marker in different tumor entities such as breast, ovarian, pancreatic, and colorectal cancers." (PMID 36681680, 2023).
glioma (continued). "Next, we tested the impact of BRAF-inhibition on the expression of the respective ETS-factors and found that only ETS1 expression, but not expression of GABPA or the different GABPB splice variants, were significantly and consistently downregulated throughout all BRAFV600E-mutated glioma." (PMID 31391125, 2019). "We further show that enhanced non-canonical NF-κB signalling promotes the co-localisation of p52 and ETS1, resulting in transcriptional activation of non-κB and/or non-ETS glioma-promoting genes." (PMID 37087499, 2023). "This demonstrated a significant overexpression of MYBL2, FOXM1, ETS1, HIF-1A, and JUN in both glioma cohorts compared to non-neoplastic brain tissues." (PMID 35228525, 2022).
systemic lupus erythematosus (32 papers, 2010 to 2025). An autoimmune multi-organ disease typically associated with vasculopathy and autoantibody production. "Examining the location of SNPs that have been associated with lupus, we found they cluster in two regions, upstream near Site 1 and within the Ets1 gene near Site 7 and sequences downstream of it." (PMID 40053568, 2025). "GWAS has established that the human ETS1 gene is a susceptibility locus for multiple autoimmune diseases, such as systemic lupus erythematosus (SLE), rheumatoid arthritis (RA), psoriasis and others." (PMID 39149372, 2024). "In keeping with this gatekeeper function, variants in ETS1 has been linked to several autoimmune conditions including systemic lupus erythematosus and multiple sclerosis." (PMID 36860866, 2023). "ETS1 is a transcription factor highly expressed in CD4 T-cells known to regulate differentiation, survival and proliferation of lymphoid cells; the ETS1 locus is an important genetic regulator of risk for the autoimmune disorder systemic lupus erythematosus." (PMID 35100265, 2022). "Ets-1-/- mouse represents another model with lupus-like features, which demonstrated enhanced Th17 differentiation following Ets-1 deficiency." (PMID 31240232, 2019). "Mutations in ETS1 have been associated with systemic lupus erythematosus (SLE), an autoimmune disease in which the role of neutrophils has become increasingly appreciated." (PMID 30696696, 2019). "In humans, single nucleotide polymorphisms in the ETS1 gene locus have been associated with multiple autoimmune and inflammatory diseases including lupus, rheumatoid arthritis, psoriasis, and atopic dermatitis." (PMID 31356162, 2019). "In humans, genome-wide association studies have detected associations of single nucleotide polymorphisms in the human ETS1 gene with autoimmune diseases, including lupus." (PMID 31356162, 2019). "The human ETS1 gene has also been identified as a susceptibility locus for development of lupus and multiple other autoimmune diseases." (PMID 31356162, 2019). "A eQTL analysis indicates that the allele of rs6590330 in ETS1 is associated with decreased ETS1 expression and increases the risk of systemic lupus erythematosus by enhancing the binding of pSTAT1." (PMID 28316886, 2017). "The risk allele of this variant confers weaker binding affinity for Ets-1, which is a transcription factor encoded by a lupus susceptibility gene found in recent GWAS." (PMID 21738483, 2011). "Transcription factor Ets-1, encoded by the lupus-susceptibility gene ETS1, identified in recent genome-wide association studies, binds near this variant." (PMID 21738483, 2011). "As members of the Asian Lupus Genetics Consortium, we have also performed a GWAS in Asian populations and have identified variants in ETS1 and WDFY4 that are associated with SLE." (PMID 21738483, 2011). "In addition, ETS1-deficient mice exhibit lupus-like symptoms, mainly characterized by high titers of autoantibodies and deposition of immune complexes in the kidneys." (PMID 40433370, 2025). "Indeed, genome-wide association studies (GWASs) have associated single-nucleotide polymorphisms (SNPs) in the human ETS1 gene locus with an increased susceptibility to systemic lupus erythematosus (SLE)." (PMID 37691956, 2023). "In addition, SNPs in ETS1 have been shown to be associated with rheumatoid arthritis and celiac disease in European populations and with systemic lupus erythematosus in Chinese populations; all of these diseases have a higher prevalence in females." (PMID 29659830, 2018). "Interestingly, two SNPs linked to skin diseases (rs3802826, psoriasis; and rs1128334, systemic lupus erythematosus) overlap “hub” gene ETS1, although both fall outside of the ETS1-linked SE domain." (PMID 28445475, 2017). "Two recent genome-wide association studies (GWASs) of an Asian population demonstrated a novel region containing ETS1 at chromosome 11q23 strongly associated with systemic lupus erythematosus (SLE)." (PMID 24708692, 2014).
systemic lupus erythematosus (continued). "Extensive genetic studies have pinpointed Ets1 as a vulnerable region for systemic lupus erythematosus and rheumatoid arthritis." (PMID 40887825, 2025). "Our present study further demonstrated that STAT1 and ETS1 were hub TFs in the tubulointerstitium, which provided evidence for the interaction of TFs in lupus." (PMID 36829595, 2023). "The levels of Ets1 mRNA are reduced in peripheral blood mononuclear cells (PBMCs) of lupus patients and are inversely correlated with the serum titers of autoantibodies against double-stranded DNA (dsDNA)." (PMID 37691956, 2023). "ETS1 and FLI1, susceptibility genes associated with systemic lupus erythematosus, were differentially expressed in CD4+ and CD8+ effector cells in G1 and G3." (PMID 36703979, 2022). "Ets-1 activation is also involved in chronical autoimmune pathologies such as rheumatoid arthritis and lupus." (PMID 35008670, 2021). "Mutations in and reduced expression of the ETS1 gene may be associated with systemic lupus erythematosus (SLE)." (PMID 31275358, 2019). "Ets1 knockout mice develop a lupus-like autoimmune disease, accompanied by aberrant B and T cell differentiation." (PMID 31356162, 2019). "Low expression levels of ETS1, leading to aberrant lymphocyte differentiation, have been found in systemic lupus erythematosus." (PMID 30037347, 2018). "Nineteen probes for 16 lupus-relevant genes (Abca1, Apobec3, Ccr7, Ceacam3, Ets1, Foxp3, Hdac1, Ifng, Irf9, Itgam, Jhdm1d, Mmp9, Oscar, Slc4a1, Tbx21, and Tlr7) were identified from the database of male murine spleen." (PMID 30246031, 2018). "ETS1 is reduced in peripheral blood mononuclear cells of SLE patients and Ets1 ablation leads to an accumulation of PCs, autoantibodies and a lupus-like phenotype in mice." (PMID 31557984, 2016). "Lack of Ets1 causes systemic lupus erythematosus (SLE) autoimmunity, correlating with the uncontrolled proliferation of T follicular helper type 2 cells." (PMID 40887825, 2025). "Four transcription factors tagged by this analysis are involved in immune-mediated diseases such as systemic lupus erythematosus, inflammatory bowel disease and multiple sclerosis (CFOS, ELF1, ETS1 and NFKB)." (PMID 28793313, 2017). "E26 transformation-specific-1 (ETS1) and WDFY family member 4 (WDFY4) are closely related with systemic lupus erythematosus." (PMID 24549174, 2014). "Supporting a role for Ets1 in autoimmunity, mice lacking Ets1 develop a lupus-like autoimmune disease, with excessive B and T cell activation and secretion of IgM and IgG autoantibodies against self-antigens." (PMID 39149372, 2024). "Mice with a conventional deletion of the Ets1 gene, where Ets1 is absent in all cell types, develop an autoimmune syndrome similar to lupus, with increased activation of both B and T cells." (PMID 31356162, 2019). "Mice lacking Ets1 (Ets1 KO mice) develop autoimmune disease, with similarities to human lupus." (PMID 37691956, 2023). "For example, the correlation between ETS-1 and miR-326 expression in CD19 + B cells is negative pathogenesis in Systemic lupus erythematosus patients." (PMID 31873148, 2019).
lung carcinoma (31 papers, 2004 to 2025). "Clinically, high expression levels of STAT1 and ETS1 are associated with poor survival outcomes in lung cancer patients." (PMID 40948762, 2025). "ETS1/2 proteins also regulate the expression of dual specificity phosphatase 6 protein which suppresses lung cancer progression by inhibiting oncogenic ERK signaling." (PMID 37107558, 2023). "In lung cancer, ETS1 contributes to transactivation of Twist1, a gene involved in tumour cell motility and dissemination, thereby worsening the condition." (PMID 34378314, 2021). "We present evidence correlating expression of Ets1 and Zeb1 in invasive lung adenocarcinoma, suggesting that this amplification loop is evident in invasive lung cancer." (PMID 25880398, 2015). "In ovarian and lung carcinomas, expression of Ets-1 has also been observed in both stromal and tumour cells." (PMID 15365563, 2004). "Likewise, ETS1 is one of the transcriptional regulators identified in the regulatory network in NSCLC lung cancer." (PMID 36551878, 2022). "In lung diseases, ETS1 acts as an oncogene and could promote cell viability and migration of lung cancer cells." (PMID 34245091, 2021). "The interaction between ETS1 and lncRNA was previously noted in lung cancer." (PMID 34378314, 2021). "Interestingly, WIPF1 was found as a downstream target of ETS1 in lung cancer." (PMID 34245091, 2021). "Lung cancer regulatory networks from trametinib-treated cells confirmed the strong involvement of the RAS-ERK signaling pathway and its positive influence on ETS1, FOSL1 and SMAD3." (PMID 41184222, 2025). "Further verification found that six hub genes were screened in relation to lung cancer, including mTOR, NF1, CHD7, ETS1, IL-6, and COL1A1." (PMID 36211008, 2022). "In lung cancer, RUNX2 directly inhibits ETS1 expression, which is likely to promote angiogenesis, proliferation, invasion, and metastasis." (PMID 36551878, 2022). "Six hub genes were screened in relation to lung cancer, including mTOR, NF1, CHD7, ETS1, IL-6, and COL1A1." (PMID 36211008, 2022). "High expression of ETS1 was also potentially correlated with poor prognosis in LUAD, and the ROC curve suggested that ETS1 had some predictive power for lung cancer prognosis." (PMID 35003395, 2021). "Interestingly, WIPF1 could be regulated by ETS1 in lung cancer." (PMID 34245091, 2021). "Here, we provide evidence that links FOXD1 with Gal-3 in lung cancer, in which FOXD1 enhanced Gal-3 expression; subsequently, Gal-3-mediated ITGβ1/ETS-1 signaling contributed to further increase FOXD1 expression." (PMID 31795213, 2019). "The HIF, TGM2, CSNK1A1, CSNK2A1, CTNNA1, NAMPT)/Visfatin, TNFRSF1A, ETS1 and SRC-1 were down-regulated and proposed as the biomarkers for lung cancer." (PMID 23122428, 2012). "Expression analysis reveals that hypoxia induced lung cancer related biomarkers, HIF and its modulating proteins (TGM2, CSNK1A1, CTNNA1, NAMPT/Visfatin, TNFRSF1A, ETS1, SRC-1, FN1, APLP2, DMBT1/SAG, AIB1 and AZIN1) are significantly down regulated." (PMID 23122428, 2012). "In the GEO database, the expression levels of MET, ETS-1, and USP9X in osimertinib-resistant lung cancer cells, as observed in the datasets GSE202859 and GSE236654, were significantly higher than those found in osimertinib-sensitive lung cancer cells." (PMID 39468027, 2024). "Likewise, in GSE253742, MET, ETS-1, and USP9X expression levels in lung cancer tissues after osimertinib treatment were elevated compared to untreated lung cancer tissues, supporting our research findings." (PMID 39468027, 2024). "In addition, six hub genes that were related to lung cancer were identified as hub genes, including mTOR, NF1, CHD7, ETS1, IL-6, and COL1A1." (PMID 36211008, 2022). "ETS1 is not dysregulated in other types of cancer; it is only dysregulated in lung cancer, suggesting that it is a crucial gene for lung tumor progression." (PMID 36551878, 2022).